SNORD116-9 (small nucleolar RNA, C/D box 116-9)
Synonyms: HBII-85-9
Gene: Small nucleolar RNA gene on chromosome 15 (25,073,107 to 25,073,201, forward strand). Ensembl gene ENSG00000206727.
Gene Ontology:
Biological process: RNA processing
Cellular component: nucleolus
Homologues: Orthologues: macaque SNORD116 (100% identical), rabbit SNORD116 (91% identical), rabbit SNORD116 (89% identical), rabbit SNORD116 (88% identical), rabbit SNORD116 (87% identical), rabbit SNORD116 (84% identical), rabbit SNORD116 (79% identical), rabbit SNORD116 (77% identical), rabbit SNORD116 (76% identical). Paralogues in human: SNORD116-3 (100% identical), SNORD116-5 (99% identical), SNORD116-7 (99% identical), SNORD116-8 (98% identical), SNORD116-1 (97% identical), SNORD116-4 (97% identical), SNORD116-2 (96% identical), SNORD116-6 (95% identical), SNORD116-14 (87% identical), SNORD116-17 (86% identical), SNORD116-19 (86% identical), SNORD116-15 (85% identical), and 20 more.